CDH9 (cadherin 9)
Description:
Cadherins are calcium-dependent cell adhesion proteins. They preferentially interact with themselves in a homophilic manner in connecting cells; cadherins may thus contribute to the sorting of heterogeneous cell types.
Tractability: Antibody: UniProt places it where antibodies can reach, with high confidence; its Gene Ontology location is reachable by antibodies, with high confidence; UniProt predicts a signal peptide or a membrane-spanning region. PROTAC: ubiquitination databases record sites on it.
Gene: Protein-coding gene on chromosome 5 (26,880,597 to 27,121,150, reverse strand). Ensembl gene ENSG00000113100.
Subcellular location: Cell membrane
Subcellular location (Human Protein Atlas): Golgi apparatus
Pathways (Reactome):
Cell-Cell communication: Adherens junctions interactions
Gene Ontology:
Molecular function: beta-catenin binding; cadherin binding; calcium ion binding
Biological process: adherens junction organization; calcium-dependent cell-cell adhesion; cell migration; cell morphogenesis; cell-cell adhesion; cell-cell adhesion mediated by cadherin; cell-cell junction assembly; synaptic membrane adhesion; cell adhesion; homophilic cell-cell adhesion
Cellular component: adherens junction; catenin complex; plasma membrane; membrane
Genetic constraint (gnomAD): Loss-of-function variants: 16 observed, 42.04 expected, observed/expected ratio (o/e) 0.38, 90% interval 0.26 to 0.58. The upper end of that interval is the gene's LOEUF score, 0.58, which puts it in group 2 of 6, group 1 being the genes least tolerant of losing a copy. Missense variants: 545 observed, 643.66 expected, observed/expected ratio (o/e) 0.85, 90% interval 0.79 to 0.91. Synonymous variants: 266 observed, 231.64 expected, observed/expected ratio (o/e) 1.15, 90% interval 1.04 to 1.27.
Homologues: Orthologues: chimpanzee CDH9 (99% identical), macaque CDH9 (99% identical), dog CDH9 (96% identical), pig CDH9 (94% identical), rabbit CDH9 (94% identical), rat Cdh9 (92% identical), guinea pig CDH9 (91% identical), mouse Cdh9 (91% identical), tropical clawed frog cdh9 (72% identical). Paralogues in human: CDH6 (72% identical), CDH10 (69% identical), CDH7 (57% identical), CDH18 (57% identical), CDH12 (57% identical), CDH20 (56% identical), CDH11 (55% identical), CDH8 (54% identical), CDH22 (51% identical), CDH19 (47% identical), CDH24 (47% identical), CDH5 (39% identical), and 21 more.
Diseases named in the same sentence as CDH9 in open-access papers:
CDH9 is named in the same sentence as 20 diseases in open-access papers, as found by Europe PMC text mining. Sharing a sentence is not in itself a finding about the gene and the disease. The quoted sentences say what the papers report.
autism (10 papers, 2011 to 2025). Persistent deficits in social interaction and communication and interaction as well as a markedly restricted repertoire of activity and interest as well as repetitive patterns of behavior. "These nearest genes include candidate genes for which strong proximal associations with autism have previously been reported, such as CDH9 and SEMA5A." (PMID 21247446, 2011). "Finally, Mir100 (paired with cadherin Cdh9), is associated with neurological disorders such as AD, schizophrenia and autism." (PMID 32093602, 2020). "The segregated expression patterns of Cdh9 and Cdh11 implies that the two genes may contribute to the determination of sub-regions of autism-associated areas in the CB." (PMID 31046797, 2019). "Participant 32 had a 5p14.1 deletion including the CDH9 gene, one of the cadherin gene members reported to play a role in autism and supported by genome-wide association studies indicating this genomic region to be highly associated with autism." (PMID 25400949, 2014). "Two of genes with SLP < −3 for the problem drinking phenotype are also possibly implicated in autism risk, ARHGAP33 (SLP = −3.69) and CDH9 (SLP = −4.59)." (PMID 33893496, 2022). "Genetic studies shows an involvement of cadherin 10 (CDH10) and cadherin 9 (CDH9) in the pathogenesis of autism." (PMID 24756565, 2014). "In addition, it was revealed that circCdh9 was also significantly downregulated in the cerebellum and upregulated in the prefrontal cortex and the amygdala of autism animal models, while both CDH9 and TRPC6 genes have been implicated in autism pathogenesis in humans." (PMID 40868063, 2025). "With recent findings by other researchers, our results suggest that CDH9 deficiency may not have a significant effect on autism traits." (PMID 34523068, 2022). "Notably, these included transcripts for adhesion proteins such as CDH13, CDH9, CDH15 and SLITRKs, all strongly linked to ASD, presynaptic molecules such as SYNIII and SV2C, associated with non-syndromic autism and SCZ, and post-synaptic transcripts such as DLGAP2 and GRIN2D, linked to SCZ." (PMID 30185603, 2018). "Although no gene reached formal significance levels, it is possibly of some interest that three genes potentially related to autism were each individually significant at P < 0.001: FOXP1, ARHGAP33 and CDH9." (PMID 33893496, 2022). "Other previously reported autism candidate genes with suggestive roles in neurite regulation include PCDH9 (1.76E-03), CDH9 (6.00E-03) and CSMD3 (2.10E-02)." (PMID 21247446, 2011). "Consistent with this prediction, behavioral studies showed that Cdh11-null mice, but not Cdh9-null mice, have multiple autism-like behavioral alterations." (PMID 34523068, 2022). "No gene was formally significant after correction for multiple testing, but three genes possibly related to autism were significant at P < 0.001, FOXP1, ARHGAP33 and CDH9, along with VGF which may also be of psychiatric interest." (PMID 33893496, 2022).
autism spectrum disorder (4 papers, 2010 to 2024). A spectrum of developmental disorders that includes autism, and Asperger syndrome. "Furthermore, both CDH9 and CDH10 have been found associated with autism spectrum disorders (ASD), suggesting that genetic variations of these cadherins impair social behavior." (PMID 39570883, 2024).
schizophrenia (3 papers, 2020 to 2021). A major psychotic disorder characterized by abnormalities in the perception or expression of reality. "Schizophrenia genes relevant to cell adhesion comprised of several members of the cadherin family CDH22, CDH4, CDH7 and CDH9 as well as the protocadherin PCDH10." (PMID 34859219, 2021).
colorectal carcinoma (1 paper, 2007). A malignant epithelial neoplasm that arises from the colon or rectum and invades through the muscularis mucosa into the submucosa. "The nominally significant intragenic SNPs were found in several genes, including cadherin 9 type 2 (CDH9) on 5p14 and gene deleted in colorectal carcinoma (DCC) on 18q21." (PMID 17903296, 2007). "More than half of these were in or near several genes, including cadherin 9 type 2 (CDH9) on 5p14, nuclear receptor subfamily 5, group A gene (NR5A2) at 1q32, gene deleted in colorectal carcinoma (DCC) on 18q21, and PPARG on 3p25." (PMID 17903296, 2007).
coronary artery calcification (1 paper, 2022). Calcification of the coronary artery, used as a measure of coronary atherosclerosis, a risk factor for myocardial infarction. "An intronic variant of CDH9 was previously implicated in coronary artery calcification (CAC) in AAs." (PMID 35886043, 2022).
fibrosis (1 paper, 2007). the formation of excess fibrous connective tissue in an organ or tissue in a reparative or reactive process. "The percentage of cadherin-9-expressing cells was three to five times higher in kidney specimens from fibrosis patients than in healthy kidneys." (PMID 17668045, 2007).
liver cancer (1 paper, 2023). An epithelial or non-epithelial malignant neoplasm that arises from the liver. "Moreover, the liver cancer-related driver genes RPS6KA3 and DYNC2H1 and the tumor migration-related gene CDH9 were also significantly different between the two groups." (PMID 37409259, 2023).
renal cell carcinoma (1 paper, 2007). "The expression pattern of cadherin-9 was also studied under two pathological conditions, renal cell carcinoma and renal fibrosis." (PMID 17668045, 2007). "Expression of cadherin-9 was also studied under pathological conditions in renal fibrosis and renal cell carcinoma, as well as in chemically induced epithelial-mesenchymal transition." (PMID 17668045, 2007). "Cadherin-9-positive cells in renal cell carcinomas display an elongated and even spindle-shaped stromal cell phenotype." (PMID 17668045, 2007). "Cadherin-9 is neither expressed by renal epithelial cells nor by any of the renal cell carcinoma cell lines examined, which were all of epithelial origin." (PMID 17668045, 2007). "Under pathological conditions, cadherin-9 was expressed in the stroma of renal cell carcinoma, but not in the tumor cells themselves, and in renal fibrosis the percentage of cadherin-9-positive cells was clearly elevated 3 to 5 times compared to healthy kidney tissue." (PMID 17668045, 2007).
renal fibrosis (1 paper, 2007). A final common manifestation of a wide variety of chronic kidney diseases characterized by glomerulosclerosis and tubulointerstitial fibrosis. "Induction of epithelial mesenchymal transition in renal epithelial cells with cyclosporin-A, which causes renal fibrosis as a side effect, induced cadherin-9 expression." (PMID 17668045, 2007). "Thus, cadherin-9 up-regulation by cyclosporin-A might be a relatively late event during EMT of renal tubular cells in renal fibrosis." (PMID 17668045, 2007). "Thus, cadherin-9 might have a role in fibroblast activation, as during development of renal fibrosis activated fibroblasts are regarded as responsible for the massive deposition of extracellular matrix, a hallmark of this pathology." (PMID 17668045, 2007).
tumor (9 papers, 2007 to 2024). "A compelling example is the SNP rs325349 (A/G) on chromosome 5 located in CDH9, for which 91.7 percent (n = 11) of the heterozygous samples showed disparity in the tumour and all shift in one direction, toward the major allele (A)." (PMID 22188678, 2011). "Despite these major clinical differences in the patient data sets, we detect a significant increase in the accessibility of NRXN1 and CDH9 chromatin sites in high-grade tumours as compared to intermediate-grade tumours." (PMID 34911933, 2021). "Cadherin 9 (CDH9) is an important protein that strengthens the interaction between immune lymphocytes and tumor cells." (PMID 34093667, 2021). "The wound healing assay reveals that inhibiting either BCL2L11 or CDH9 will enhance the migration of cell lines, which provides evidence that these two genes are suppressors of tumor metastasis." (PMID 28855549, 2017). "Notably, genomic regions associated with the neuronal adhesion genes, NRXN1, NLGN1 and CDH9, are highly accessible in Gleason pattern 4 vs. 3 tumours." (PMID 34911933, 2021). "We also observed some additional putative regulatory interactions in Gleason pattern 4 tumours around the NLGN1 and CDH9 loci, even though the increase in the number of links were not as high as around the NRXN1 locus." (PMID 34911933, 2021). "To validate our results that show a significant enrichment in the chromatin accessibility profiles of high-grade tumours for neuronal adhesion molecules NRXN1, NLGN1 and CDH9, we analyzed the bulk ATAC-seq profiles using the TCGA PRAD data set35." (PMID 34911933, 2021). "However, the role of CDH9 on tumor invasion and metastasis is unclear, and we could not find any reference that associated CDH9 with metastasis, migration, or invasion." (PMID 28855549, 2017). "Cadherin-9 was not expressed by renal tumor cells or leukocytes, as clearly demonstrated in RCC tissues which showed cadherin-9 expression only in the stromal compartment, but not in tumor cells or leukocyte infiltrates." (PMID 17668045, 2007).
cancer (6 papers, 2014 to 2024). A tumor composed of atypical neoplastic, often pleomorphic cells that invade other tissues. "We are also the first to report and verify that CDH9 is a suppressor of cancer metastasis." (PMID 28855549, 2017). "Hence, both BCL2L11 and CDH9 are highly likely to be suppressors of cancer metastasis, which agrees with our hypothesis." (PMID 28855549, 2017). "The expression of several cancer metastasis-related genes such as ADAM9, CDH9 and CD44 was increased following miR-182 knockdown." (PMID 24519909, 2014). "Many of these other potential enhancer-hijacking targets do not have well-established roles in cancer pathogenesis, however, we did notice a number of genes involved in cell adhesion (ALCAM, NCAM2, CADM2, and CDH9) and 2 SLIT and NTRK like family members (SLITRK1, SLITRK6)." (PMID 35538064, 2022).
neurological disorders (2 papers, 2020 to 2024). "OMG, LRTM2, GRIK1, and CDH9 are predominantly expressed in the nervous system, participating in neuronal and synaptic functions, has a significant impact on the occurrence of various neurological disorders." (PMID 38979414, 2024).
psychiatric diseases (2 papers, 2021 to 2022). "Several recent genetic studies have implicated two type II cadherins, CDH11 and CDH9, in ASD and other psychiatric diseases." (PMID 34523068, 2022).
CDH9 also shares sentences with these, for which no sentence is quoted: Aphasia (1 paper); Autoimmunity (1); bipolar disorder (1); depression (1); epilepsy (1); glioma (1); ovarian carcinoma (1).